C1orf185 (chromosome 1 open reading frame 185)
Synonyms: FLJ27485
Tractability: Antibody: UniProt predicts a signal peptide or a membrane-spanning region.
Gene: Protein-coding gene on chromosome 1 (51,102,221 to 51,148,086, forward strand). Ensembl gene ENSG00000204006.
Subcellular location: Membrane
Gene Ontology:
Cellular component: membrane
Genetic constraint (gnomAD): Loss-of-function variants: 8 observed, 8.31 expected, observed/expected ratio (o/e) 0.96, 90% interval 0.56 to 1.67. That is too few expected variants to judge how well the gene tolerates losing a copy. Missense variants: 145 observed, 156.39 expected, observed/expected ratio (o/e) 0.93, 90% interval 0.81 to 1.06. Synonymous variants: 57 observed, 58.87 expected, observed/expected ratio (o/e) 0.97, 90% interval 0.78 to 1.21.
Homologues: Orthologues: chimpanzee C1H1orf185 (98% identical), pig C1orf185 (84% identical), dog C1orf185 (82% identical), rabbit C1orf185 (80% identical), macaque C1H1orf185 (58% identical), rat C5h1orf185 (56% identical), mouse 4930522H14Rik (56% identical).